XPC (XPC complex subunit, DNA damage recognition and repair factor)
Diseases named in the same sentence as XPC in open-access papers (continued):
Sharing a sentence is not in itself a finding about the gene and the disease.
XPC also shares sentences with these, for which no sentence is quoted: adenocarcinoma (4 papers); anemia (2); autosomal recessive disease (2); genodermatosis (2); hereditary cancer syndrome (2); infection (2); lymphoma (2); mesothelioma (2); metastatic melanoma (2); small cell lung carcinoma (2); thyroid tumor (2); Xeroderma pigmentosum group (2); acute leukemia (1); anaplastic large cell lymphoma (1); astrocytoma (1); atypical teratoid rhabdoid tumor (1); basal cell carcinoma (1); breast sarcoma (1); breast tumors (1); Burkitt lymphoma (1); cerebro-oculo-facio-skeletal syndrome (1); CNS tumors (1); colorectal adenocarcinoma (1); colorectal polyps (1); Crohn disease (1); de Sanctis-Cacchione syndrome (1); embryonal carcinoma (1); embryonal rhabdomyosarcoma (1); endometrial cancer (1); ependymoma (1).
A further 28 diseases each share a sentence with XPC in 1 paper.